IL17A (interleukin 17A)
Diseases named in the same sentence as IL17A in open-access papers (continued):
Sharing a sentence is not in itself a finding about the gene and the disease.
autoimmune disease (continued). "To date, no medical therapy has proven unequivocal benefit concerning clinical outcomes of PSC, but dysregulation in the JAK-STAT pathway is considered an important step in the pathogenesis of several inflammatory and autoimmune diseases with a prominent IL-6, IFN gamma, and IL-17A signature." (PMID 37256725, 2023). "Autoimmune disorders can lead to inflammation and chronic pain; therefore, we focused on the autoimmune-related protease-activated receptor 2 (PAR2/F2RL1) and interleukin 17A (IL-17A/IL17A) genes." (PMID 38139455, 2023). "In addition, Bhlhe40 seems to be required for Th1 and Th17 effector cytokine production, including IL-17A, GM-CSF and IFN-γ, in the context of autoimmune disease, GVHD, and Toxoplasma gondii infection models." (PMID 37121980, 2023). "Studies have shown that Treg cells prevent the occurrence of autoimmune diseases critically depending on the effect factors TGF-β and IL-10, while Th17 cells promote autoimmune and inflammatory processes mainly by secreting IL-17A closely involved with the severity of IBDs." (PMID 36304936, 2022). "For the sake of space restrictions, we will not address the role of IL-17A in other autoimmune diseases or rheumatic musculoskeletal diseases." (PMID 35620115, 2022). "Besides, a preceding study investigates the correlation between MALT1 expression and clinical features in autoimmune diseases: MALT1 is positively related to CRP, TNF‐α, and IL‐17A in inflammatory bowel disease patients." (PMID 35622982, 2022). "IL-17F-/- mice showed a higher resistance to IBD induction as compared with IL-17A knockout mice, and neutralization of IL-17F, not IL-17A, alleviated colitis progression in mice, indicating a pathologic role of IL-17F in autoimmune disease." (PMID 32391010, 2020). "First, because chronic infections, gestational diabetes and autoimmune disease can influence IL-17A production, we recruited patients who did not have these diseases." (PMID 32477272, 2020). "Neutralizing IL-17C is an intriguing approach in the treatment of autoimmune diseases as it might hamper TH17 function in general and not only the impact signaling of the signature cytokine IL-17A." (PMID 32174926, 2020). "The downregulated expression of IL-17A and IL-6 after DIM treatment was similar to that observed in mice with autoimmune diseases such as colitis and experimental autoimmune encephalomyelitis, in which IL-17A and IL-6 expression was also suppressed by DIM treatment." (PMID 33175869, 2020). "After verification of the induction of GLK–AhR–ROR-γt–IL-17A signaling in human SLE T cells, we next studied whether the GLK–AhR–ROR-γt signaling is a therapeutic target for autoimmune diseases." (PMID 31318609, 2019). "In conclusion, we have provided evidence that RFX1 downregulation contributes to the increased IL-17A expression and Th17 cell differentiation in the CD4+ T cells of patients with SLE, as well as promotes the pathologic changes of autoimmune diseases including EAE and lupus-like mice models." (PMID 29422534, 2018). "Various inflammatory cytokines could promote the differentiation from naïve T cells into functional T cells, which as well as macrophages are involved in various autoimmune diseases by secreting IFN-γ and IL-17A and so on." (PMID 28446897, 2017). "Since miR-23b acts as an oncosuppressor in types of cancers and regulates the IL-17-mediated proinflammatory signaling pathways in autoimmune disease, it is meaningful to reveal the role of miR-23b in TSCC development and the regulatory relationship between IL-17A and miR-23b." (PMID 28035060, 2017). "Antibodies that neutralize IL-17A or its receptor (IL-17RA) deliver efficacy in autoimmune diseases, but no small-molecule IL-17A antagonists have yet progressed into clinical trials." (PMID 27527709, 2016).
autoimmune disease (continued). "IL17A, along with five functional homodimers (IL17B-F), one heterodimer (IL17A/F), and 5 receptors (IL17RA-RE), composes the IL17 family, which is important to adaptive immunity responses, namely, as mediator of chronic inflammation and autoimmune diseases." (PMID 26788019, 2015). "As Th17 as well as IFN-γ contributes for pathogenesis of autoimmune diseases, the reduction of T cells that secrete IL-17A and IFN-γ might halt or reverse harmful autoimmune processes in subjects with autoimmune disease." (PMID 26053099, 2015). "Nor, in contrast to a recent report on antigen + adjuvant induced autoimmune diseases, could we demonstrate differences in the Th17 population—either the fraction of CD4+ cells expressing IL-17A or its expression level." (PMID 25407682, 2014). "Moreover, RAC1 activation can be directly induced by IL17A and RAC1 inhibitory peptide has been found to suppress T cell activation and autoantibody production in autoimmune disease." (PMID 25544849, 2014). "These cells can induce autoimmune disorders by their production of IL-17A and IL-22, even though IL-17A-producing iNKT cells are not restricted to a particular iNKT cell subset." (PMID 22346732, 2012). "But importantly, IL-1β and IL-6, both found to be increased in VERA patients, are known to promote the differentiation of Th17 cells, which in turn secrete IL-17A and IL-22, two cytokines that were elevated in VERA patients and have an essential function in the pathogenesis of autoimmune diseases." (PMID 20961415, 2010). "Given that IL17A‐targeted monoclonal antibodies (e.g., secukinumab) are already FDA‐approved for autoimmune diseases with well‐characterised safety profiles, combining such agents with neoantigen or ENO1 vaccines could be rapidly tested in early‐phase PDA trials." (PMID 40831074, 2025). "Puel and colleagues detected high titer AAbs to one or more of IL-17A, IL-17F and/or IL-22 in 33 patients with APECED, but not in patients with other autoimmune disease or healthy controls, and demonstrated functional inhibition of IL-17A in vitro using plasma from one of these patients." (PMID 31557985, 2016). "We used enzyme-linked immunosorbent assays (ELISAs) to measure the cytokine interleukin-17A (IL-17A) in the serum of ALS patients (n = 32; 28 sporadic ALS (sALS) and 4 familial ALS (fALS)) and control subjects (n = 14; 10 healthy subjects and 4 with autoimmune disorders)." (PMID 21062492, 2010). "Flow cytometry analysis of the composition of T-cells producing IFN-γ (Th1), IL-17A (Th17), IL-4 (Th2), and IL-10 (Treg) revealed no visible changes in the percentage of Th1 and Treg cells in response to various exosomes for both MS patients and control subjects without autoimmune disease." (PMID 37108633, 2023). "It has been reported that IL-17A serum concentrations in sporadic ALS and familial ALS patients are significantly higher than control subjects without autoimmune disorders." (PMID 33132897, 2020). "Furthermore, non-photoactivated VP also inhibited IL-17A production by the AhR-RORγt complex by targeting GLK, which is suggestive of a potential therapeutic effect against Th17-mediated autoimmune diseases." (PMID 33178014, 2020). "Lastly, infection and autoimmune diseases may influence both the count of Th17 cells and CD4+ Tregs as well as their IL-17A expression, we did, however, not factor those in as potential confounders." (PMID 31681282, 2019).
rheumatoid arthritis (1,094 papers, 2005 to 2026). A chronic, systemic autoimmune disorder characterized by inflammation in the synovial membranes and articular surfaces. "Many of the cytokines dysregulated in periodontitis, such as IL-6, TNF-α, and IL-17A, play pathogenic roles in conditions like cardiovascular disease, rheumatoid arthritis, diabetes, stress, and certain cancers." (PMID 38891939, 2024). "Elevated IL-17A levels are associated with rheumatoid arthritis, multiple sclerosis, and inflammatory bowel disease, highlighting its notable role in immune regulation and inflammation." (PMID 38892253, 2024). "The IL-17A rs8193036 variant genotype has been previously associated with an increased risk of rheumatoid arthritis (RA) in the Chinese population." (PMID 39125893, 2024). "The expression of both IL-17A and IL-17F is detectable within synovial tissue, and their presence has been implicated in the pathogenesis of rheumatoid arthritis (R." (PMID 37751416, 2023). "IL-17A has been implicated in many inflammatory diseases, such as rheumatoid arthritis, asthma, systemic lupus erythematosus (SLE), and allograft rejection." (PMID 36277038, 2022). "For example, there are studies of single nucleotide polymorphisms (SNPs) in IL17A associated with rheumatoid arthritis (RA) and systemic lupus erythematosus (SLE)." (PMID 33672430, 2021). "IL-17A was recently demonstrated to be a novel predictor of vascular dysfunction in rheumatoid arthritis, and elevated plasma levels of IL-17A are associated with cardiovascular risk." (PMID 33322218, 2020). "IL-17A signaling has been associated with several inflammatory diseases in humans, such as rheumatoid arthritis, systemic lupus erythematosus, and Crohn’s disease." (PMID 33304351, 2020). "The profibrotic effect of IL-17A and elevated IL-17RA in human individuals with idiopathic pulmonary fibrosis and rheumatoid arthritis-associated lung disease has already been established." (PMID 31396305, 2019). "A weak association between rheumatoid arthritis and the promoter IL17A rs2275913 was found in the Norwegian population and more recently in the Brazilian population." (PMID 29849482, 2018). "Interleukin-17A (IL-17) is a pro-inflammatory cytokine that has been implicated in inflammatory diseases such as rheumatoid arthritis." (PMID 28399156, 2017). "High levels of IL-17A are reportedly associated with several chronic inflammatory diseases including rheumatoid arthritis and multiple sclerosis." (PMID 25705127, 2015). "Thereafter, several studies revealed the association between IL17A rs2275913 G > A and rheumatoid arthritis, gastric carcinogenesis and asthma." (PMID 22827846, 2012). "The IL-17 family of cytokines, which includes the T cell–derived proinflammatory cytokines IL-17A and IL-17F, has been implicated in the pathogenesis of rheumatoid arthritis (RA) and, more recently, juvenile idiopathic arthritis (JIA)." (PMID 18311821, 2008). "While this IL17A‐OSM (neutrophil) axis has been traditionally implicated in the pathogenesis of rheumatoid arthritis, evidence has suggested it may also play a role in the onset of KOA." (PMID 38111237, 2024). "Th17-cells that may produce IL-17A have a significant pathogenic role in chronic inflammatory diseases like rheumatoid arthritis by osteoclastic bone resorption and IL-17 mRNA is detectable in biopsies from cutaneous inflammation (lesion from psoriatic skin)." (PMID 38542367, 2024). "Seven hub genes IL10, IL4, IL6, IFNG, IL1B, TNF and IL17A might be responsible for causing Colitis and Arthritis, except for Rheumatoid Arthritis." (PMID 36989283, 2023). "Additionally, IL-17A plays a major protective role against bone loss resulting from P. gingivalis-induced periodontal disease; however, numerous studies have demonstrated that IL-17A is associated with bone erosion in rheumatoid arthritis." (PMID 37623290, 2023).
rheumatoid arthritis (continued). "Several studies have reported a significant association of IL17A rs2275913 and rs8193036 polymorphisms with inflammatory disorders such as inflammatory bowel disease, autoimmune thyroid disease, ulcerative colitis, rheumatoid arthritis, Behcet’s disease, etc.." (PMID 35046957, 2021). "IL-17 (IL-17A) is a pleiotropic cytokine which has been implicated in the pathogenic development of autoimmune inflammations such as rheumatoid arthritis (RA) and multiple sclerosis (MS), but this cytokine has also been associated with protection against bacterial infections." (PMID 31333658, 2019). "Preservation buffers such as glycerol at room temperature may promote the selective growth of bacteria such as Collinsella, which has been linked to production of inflammatory cytokine IL-17A and disease states such as rheumatoid arthritis." (PMID 29844978, 2018). "In arthritic mice or rheumatoid arthritis (RA) patients, an increase in MDSCs, which could ameliorate disease symptoms, causes decreased IL-17A gene expression and Th17 cells accumulation." (PMID 27007054, 2016). "To date, there are some studies related to IL-17A G-197A (rs227593) and IL-17F A7488G (His161Arg, rs763780) gene SNPs and risk of tuberculosis (TB), gastric cancer, rheumatoid arthritis (RA), intestinal bowel disease (IBD), Crohn's disease (CD), ulcerative colitis (UC), and others." (PMID 25431761, 2014). "IL-17A and IL-17F genes are mapped on the same chromosome at position 6p12, and the polymorphisms of IL-17A G197A (rs2275913) and IL-17F C7488T (rs763780) have recently been associated with higher susceptibility to rheumatoid arthritis and ulcerative colitis." (PMID 23304063, 2012). "Recently, IL-17A has been implicated in sustaining established rheumatoid arthritis." (PMID 22028860, 2011). "In the Indigenous Americans component, the strongest signal occurs in chr 6p12.3-2; this region harbors numerous genes, including IL17A which is associated with chronic inflammatory diseases such as rheumatoid arthritis, and PKHD1 which is associated with polycystic kidney disease." (PMID 22194699, 2011). "The inflammatory effects of IL-17A are also implicated in bone destruction observed in rheumatoid arthritis (RA)." (PMID 36140808, 2022). "Thus, based on previous research focused on rheumatoid arthritis and osteoarthritis, we hypothesized that IL-17A rs2275913 and IL-17 rs763780 might influence AS susceptibility." (PMID 34744511, 2021). "The genus Collinsella within the family Coriobacteriaceae has been previously linked to rheumatoid arthritis and has showed a strong correlation with high levels of alpha-aminoadipic acid and asparagine, as well as the production of the proinflammatory cytokine IL-17A." (PMID 34026662, 2021). "IL-17A is a member of IL-17 families and is a pro-inflammatory cytokine associated with many inflammatory diseases, such as rheumatoid arthritis (RA), ankylosing spondylitis, and systemic lupus erythematosus." (PMID 31842922, 2019). "Given that proinflammatory cytokines, such as TNF-α, IL-6, and IL-17A are crucial inflammatory mediators in synovitis and subsequent tissue damage in rheumatoid arthritis (RA), gut dysbiosis has been implicated in the pathogenesis of RA." (PMID 31652955, 2019). "It is now known that IL-17A has pro-inflammatory effects on a wide range of cellular targets, such as epithelium, endothelium, and monocytes/macrophages, and plays pathogenic roles in some organ-specific autoimmune diseases, such as rheumatoid arthritis (RA) and multiple sclerosis, as well as IBD." (PMID 24586980, 2014). "Alternatively, IL-18 binding protein (IL-18BP), used as a decoy receptor for IL-18, attenuated levels of IL-17A production in a rheumatoid arthritis model." (PMID 40777291, 2025).
rheumatoid arthritis (continued). "IL-6 is typically recognized as a pro-inflammatory cytokine that promotes the differentiation of Th17 cells, contributing significantly to autoimmune conditions like rheumatoid arthritis through its role in inducing IL-17A secretion." (PMID 39768138, 2024). "Collinsella and Anaerostipes have limited evidence in irAEs, but the Collinsella genus has been reported to increase the production of IL-17A and enhance rheumatoid arthritis severity." (PMID 38475836, 2024). "Unchecked expression of IL-17a leads to autoimmunity and endothelial vascular activation, as seen in various diseases like psoriasis or rheumatoid arthritis." (PMID 38612795, 2024). "After binding to the IL-17 receptor (IL-17R), IL-17A is functionally involved in the pathogenesis of several autoimmune diseases, such as psoriasis, rheumatoid arthritis (RA), lupus, inflammatory bowel disease (IBD), and multiple sclerosis (MS)." (PMID 39057079, 2024). "In rheumatoid arthritis, IL-17A contributes to joint inflammation and damage by stimulating the production of proinflammatory cytokines and matrix metalloproteinases." (PMID 38892253, 2024). "Clinical trials targeting IL-17A in rheumatoid arthritis and uveitis have reported disappointing results." (PMID 38007487, 2023). "IL-6 and IL-17A can promote articular cartilage and bone damage; the concentration of IP-10 and IL-12 is closely related to the pathogenesis of rheumatoid arthritis." (PMID 37537628, 2023). "IL-17A, secreted by helper T cells, contributed to rheumatoid arthritis-induced PF through the IL-17A/IL-17RA regulatory axis." (PMID 37446052, 2023). "In all skin and synovial fluid samples collected from patients diagnosed with psoriatic arthritis, MC and IL-17A concentrations were significantly increased compared to patients with rheumatoid arthritis." (PMID 37629547, 2023). "FARP is negatively correlated with Th17 cell numbers and IL-17A levels in the serum of patients with rheumatoid arthritis." (PMID 36908596, 2023). "Overproduced cytokines of Th17 cells, especially IL-17A, IL-17F, IL-21, and IL-22, play a role in osteodestructive diseases such as rheumatoid arthritis (RA) and PD." (PMID 36983201, 2023). "have shown that IL-17A plays a major protective role in bone loss in Porphyromonas gingivalis induced periodontitis, although a large number of researches have shown that IL-17A is closely related to bone erosion in rheumatoid arthritis." (PMID 35371044, 2022). "IL-17A can stimulate FLSs to secrete IL-32 which further induces CD4 (+) T cells to produce IL-17A in patients with rheumatoid arthritis." (PMID 35371044, 2022). "More importantly, Collinsella has been shown to influence the epithelial production of IL-17A and contribute to hyper-permeability of the gut by reducing the expression of the tight junction protein ZO-1 in research of rheumatoid arthritis." (PMID 34869080, 2021). "Secukinumab, a human monoclonal antibody that directly inhibits IL-17A, has shown efficacy in treating immune-mediated inflammatory diseases such as psoriasis, ankylosing spondylitis (AS) (13-, 15), and rheumatoid arthritis (RA) (16-, 18)." (PMID 34614111, 2021). "High levels of soluble Sema5A are found in the serum of patients with rheumatoid arthritis, where IL-17A triggers changes in the synovium that lead to synovitis and maintain local inflammation." (PMID 33801296, 2021). "The effects of IL-17A and anti-IL-17A treatment have also been proved in asthma, rheumatoid arthritis, multiple sclerosis, transplant rejection, and inflammatory bowel disease." (PMID 33101005, 2020). "Treatment of synoviocytes from patients with rheumatoid arthritis with either recombinant IL-17A or IL-17F, in the presence of TNF, has been shown to induce a qualitatively similar gene signature." (PMID 32973785, 2020). "Secukinumab is a novel IL-17A inhibitor that has been confirmed to be effective for treating psoriatic arthritis (PsA) and rheumatoid arthritis (RA)." (PMID 33192173, 2020).